HPX (hemopexin)
Diseases named in the same sentence as HPX in open-access papers (continued):
Sharing a sentence is not in itself a finding about the gene and the disease.
cancer (continued). "We performed in vitro assays based on the hypothesis that hemopexin is secreted from CAF and affects cancer cells." (PMID 32663208, 2020). "Hemopexin as well as syntaxin-binding protein are also described as EV components released from cancer and other non-cancer cells, but their putative roles in radiation response are so far unclear." (PMID 32230970, 2020). "Hemopexin and FTL were mainly expressed in the cancer-cell cytoplasm and stromal fibroblasts." (PMID 32663208, 2020). "HPX is known to modulate the immune system, and this receptor interacts with a cell surface and highly glycosylated protein, CD200, to reduce myeloid activity in inflammation and may block cancer cell activities." (PMID 41384245, 2025). "However, hemopexin expression in cancer tissue has not been previously reported, and how hemopexin functions in cancer remains unclear." (PMID 32663208, 2020).
tumor (20 papers, 2006 to 2025). "Given its association with patient survival and tumor behavior, HPX is associated with protective outcomes and a potential therapeutic target in HCC." (PMID 41008813, 2025). "Importantly, HPX was associated with a tumor-suppressive phenotype and increased apoptosis, consistent with TNF-α-mediated mitochondrial signaling, offering new insights into HCC pathogenesis and therapy." (PMID 41008813, 2025). "These proteins (haptoglobin, ceruloplasmin, and hemopexin) are components of serum, suggesting that the large number of serum proteins in both the Pap test fluid and swab underlies the similarity of these samples relative to the tumor sample." (PMID 33413078, 2021). "Thus, in this study, we demonstrate, for the first time, by proteomic analysis of the tumor stroma, that hemopexin is a previously unrecognized LN-metastasis-associated protein of PDAC." (PMID 32663208, 2020). "This study defines novel molecular subtypes of HCC and reveals that HPX exerts anti-tumor effects through TNF-α-mediated mitochondrial apoptosis, characterized by an increased Bax/Bcl-2 ratio." (PMID 41008813, 2025). "Tumor volume measurements over time revealed that HPX overexpression markedly suppressed tumor growth, which was further supported by the significantly reduced tumor weights observed at endpoint." (PMID 41008813, 2025). "Tumors derived from HPX-overexpressed cells were significantly smaller in size compared to controls, as shown by representative images, indicating that HPX inhibits tumor growth in vivo." (PMID 41008813, 2025). "Collectively, these results demonstrate that HPX overexpression suppresses tumor growth and promotes apoptosis through modulation of apoptosis-related proteins in vivo." (PMID 41008813, 2025). "Both in vitro and in vivo experiments demonstrated that HPX overexpression significantly enhances apoptosis, thereby suppressing tumor growth and metastatic potential." (PMID 41008813, 2025). "Functional assays in multiple HCC cell lines and mouse models showed that increasing HPX levels reduced tumor growth and promoted programmed cell death through mitochondrial pathways linked to tumor necrosis factor-α." (PMID 41008813, 2025). "While those studies emphasize HPX’s function in regulating tumor proliferation and metastasis through heme clearance, our research highlights its direct involvement in promoting apoptosis in HCC, indicating potentially distinct but complementary mechanisms." (PMID 41008813, 2025). "In the BF-TK/GCV/BF-TK group, the top five hub proteins were AMBP, HRG, APCS, HPX, and GIG25; some proteins (HRG, HPX, and GIG25) are positively associated with tumor metastasis." (PMID 37511481, 2023). "Among various ductal proteins, lipophilin-B, beta-globin, hemopexin, and vitamin-D-binding protein have been found overexpressed in nipple exudate from samples of tumor-bearing breasts." (PMID 35877371, 2022). "Hemopexin (HPX) has been described to be downregulated in urine from PCa patients compared to tumor free men, an observation that is in concordance with our findings." (PMID 35267445, 2022). "It is interesting to find that F2, ITIH4, and HPX proteins were mainly expressed in tumor cells of GBC tissues, but these proteins were located mainly in inflammatory cells of control tissues not normal gallbladder epithelium." (PMID 33718182, 2021). "For practical applications of hemopexin, further investigation must be conducted to elucidate the mechanisms by which hemopexin activates tumor invasion." (PMID 32663208, 2020). "At the tumor microenvironment level, we found that HPX was closely related to hepatocytes, adipocytes, and endothelial cells and may play an important biological role in HCC." (PMID 41008813, 2025). "Functional experiments demonstrated that HPX aligned with suppression of tumor phenotypes." (PMID 41008813, 2025).
tumor (continued). "Histological analysis indicated typical tumor morphology (H&E staining) alongside enhanced expression of the pro-apoptotic marker Caspase-3 and Bax and decreased expression of the anti-apoptotic protein Bcl-2 in HPX-overexpressed tumors compared to controls." (PMID 41008813, 2025). "Alpha2HS-glycoprotein [Heavy:Light (H:L) ratio 0.63] was underexpressed in NAF from tumor-bearing breasts, while lipophilin B (H:L ratio 1.42), beta-globin (H:L ratio 1.98), hemopexin (H:L ratio 1.73), and vitamin D-binding protein precursor (H:L ratio 1.82) were overexpressed." (PMID 16542425, 2006). "However, the functions of HPX are complex and exhibit tumor-type-specific heterogeneity." (PMID 41008813, 2025). "Hemopexin may block heme-driven tumor growth and metastasis." (PMID 36718454, 2023). "We then examined the mRNA levels of CPLANE1 and hemopexin in a small cohort of PNI+ and PNI- tumor samples and found significant upregulation of CPLANE1 in PNI+ cases, validating the proteomics results." (PMID 40628700, 2025). "Among these genes, hemopexin (HPX), a secreted protein that scavenges free heme, consistently showed a tumor-suppressive pattern in HCC." (PMID 41008813, 2025). "S100A9 supports proliferation and metastasis in other tumor types; S100A9, hemopexin, and inter-alpha-trypsin inhibitor heavy chain H4 (ITIH4) were identified in saliva of patients with RCC and were suggested as potential biomarkers for disease screening." (PMID 34572331, 2021). "Hemopexin (HPX) was identified as the top candidate and functionally validated: HPX overexpression suppressed clonogenicity and migration, promoted apoptosis, and inhibited xenograft tumor growth." (PMID 41008813, 2025). "Tissue staining further revealed that KRT13, PEDF, and HPX are predominantly expressed in basal cells of the benign tissue, whereas they are not detected in tumor areas where basal cells have been lost." (PMID 35267445, 2022). "First, hemopexin function was not adequately investigated: how hemopexin mechanistically contributes to tumor progression is unclear." (PMID 32663208, 2020). "Interestingly, iron carrier proteins (Hemopexin and Serotransferrin) were only identified in EVs shed by the CSC-enriched tumor cell population of all three MB cell lines analyzed." (PMID 26464805, 2015). "Overexpression of lipophilin B, beta-globin, and hemopexin has also been confirmed in tumor-bearing tissues using non-ICAT techniques." (PMID 16542425, 2006).
bacterial infection (2 papers, 2017 to 2025). "Hemopexin is part of the acute-phase response during bacterial infection by binding iron, hence preventing its use by the bacteria." (PMID 28046109, 2017).
blood disorders (2 papers, 2023 to 2025). "This review aims to provide a comprehensive overview of HPX’s roles in the progression and prognosis of hematological diseases." (PMID 38022615, 2023). "As such, the clearance of heme is of utmost importance in certain hematologic disorders, especially when hemolysis depletes plasma Hp, leaving HPX as a critical second-line defense following hemolysis." (PMID 38022615, 2023).
Neurological disease (2 papers, 2011 to 2021). "Increased levels of hemopexin and T-kininogen 1 have been previously reported in neurological disorders." (PMID 21696593, 2011). "The network “Cellular assembly and organization, Neurological disease, Organismal development” was predicted with a high score for EAE-16d in IPA and involved the acute phase proteins HEMO (hemopexin, gene: HPX), A1AT (alpha-1-antitrypsin 1–1, gene: SERPINA1) and CO3 (complement 3, gene: C3)." (PMID 33785790, 2021).
adenocarcinoma (1 paper, 2022). A common cancer characterized by the presence of malignant glandular cells. "We observed basal cell staining for KRT13, PEDF, and HPX in benign regions of the gland, a cell type that is absent in acinar-type adenocarcinomas." (PMID 35267445, 2022).
brain diseases (1 paper, 2023). "Based on the multifunction of these proteins in several brain diseases, we first propose that Gc-globulin, ApoA1, PI3K/AKT pathway, and acute phase response proteins (hemopexin and cluster of alpha-2-macroglobulin) could be potential candidates for the diagnosis and treatment of SAE." (PMID 36600206, 2023).
immune dysfunction (1 paper, 2025). "Notably, aging is associated with reduced HPX levels, which may contribute to increased heme medicated immune dysfunction." (PMID 40221420, 2025).
kidney (1 paper, 2024). "Under hemolytic stress, hemopexin deficiency led to acute kidney injury in SCD mice, which was protected by pretreatment with purified hemopexin." (PMID 39459368, 2024).
neurodegenerative disease (1 paper, 2024). A disorder of the central nervous system characterized by gradual and progressive loss of neural tissue and neurologic function. "Hemopexin (HPX) and Alpha-1-microglobulin (A1M) are heme binding proteins that detoxify free heme and maintain iron homeostasis, playing a crucial role in mitigating the deleterious effects of heme dysregulation in neurodegenerative diseases." (PMID 39765770, 2024).
HPX also shares sentences with these, for which no sentence is quoted: colorectal cancer (3 papers); renal disease (3); acute respiratory distress syndrome (2); Alzheimer disease (2); Dengue hemorrhagic fever (2); Hepatitis (2); malignant melanoma (2); parasitemia (2); aceruloplasminemia (1); adult respiratory distress syndrome (1); aneurysm (1); bladder cancer (1); brain injury (1); cardiovascular disease (1); cerebral infarction (1); cerebral malaria (1); cervical disease (1); cognitive decline (1); cystitis (1); diabetic nephropathy (1); dysplasia (1); epilepsy (1); erythropoietic protoporphyria (1); fetal growth restriction (1); hemochromatosis (1); hemoglobinopathies (1); hemophilia (1); hemorrhage (1); hemorrhagic stroke (1); hepatitis B (1).
A further 21 diseases each share a sentence with HPX in 1 paper.